CD24 (CD24 molecule)
Diseases named in the same sentence as CD24 in open-access papers (continued):
Sharing a sentence is not in itself a finding about the gene and the disease.
cancer (continued). "Cancer stem cells are a small-specific subpopulation characterized by self-renewal and differentiation capabilities and are identified by the expression of distinct cell surface markers such as CD133, CD44, CD90, CD24, and CD73." (PMID 35713728, 2022). "However, the data on the expression of stem cell markers CD44, CD24, and ALDH1A1 in benign breast tissue of cancer-free women remains extremely limited." (PMID 36590957, 2022). "In addition, the HIF1A protein is overexpressed in hypoxic tumors; the cancer stem cell marker CD24 is also overexpressed in many tumors, confirming the correlation whereby HIF1A leads to CD24 overexpression in hypoxic tumors." (PMID 35659268, 2022). "Importantly, we identified that the CD24, CD133, and CD147 genes are regulated by promoter DNA hypermethylation in a cancer-specific manner in OSCC cell lines, and we validated this phenomenon in primary OSCC tumors with frequent hypermethylation." (PMID 36498950, 2022). "As some preclinical studies and clinical data have demonstrated the promise of targeting phagocytosis checkpoints, macrophage phagocytosis checkpoints, including CD47, CD24, stanniocalcin 1 (STC1), are potential targets for cancer immunotherapy in patients with advanced cancers." (PMID 35152264, 2022). "Notably, alcohol dehydrogenase-1 family member A1 (ALDH1A1) is a marker of chemoresistance and cancer stem-like properties in addition to CD44 and CD24." (PMID 35892853, 2022). "In vitro studies further verified that the CD24−/CD44+ cancer cell population exhibited a self-renewal capacity and could differentiate into bulk cancer cells." (PMID 36230903, 2022). "To investigate the relationship between the niche factor dependency and cancer stem cell populations, we evaluated the correlation between niche factor dependency and the expression levels of PDAC stem cell markers including CD44, CD24, and CD133." (PMID 35272688, 2022). "CD24 can interact with important adhesion molecules, including P-selectin, E-selectin, and L1CAM (CD171) and activate integrins, thus perhaps participating in leukocyte extravasation in inflammation and cancer metastasis." (PMID 33915986, 2021). "LCN2 silencing also significantly reduced the percentage of cancer stem cell populations in LCN2‐silenced IBC cells relative to control, as shown by reductions in primary and secondary mammosphere formation efficiency and CD44+CD24− cell subpopulations." (PMID 34342930, 2021). "Furthermore, in cancers resistant to CD47 blockade, anti-CD24 mAb enhance the phagocytic ability of macrophages, indicating there is a synergistic effect between CD24 interference and anti-CD47/SIRPα treatment." (PMID 34625124, 2021). "The panel of basic antigens allowed us to discriminate the cancer and non-cancer phenotypes by CD24 expression and to show that in general, the cancer samples often demonstrate a “low-expressing” phenotype based on significantly diminished expression of CD24." (PMID 34019593, 2021). "Since CD44+CD24– stem cell-like TNBC phenotype and PD-L1 upregulation require STAT3 signaling, these studies support our findings that the STAT3-activating property of PARPi can promote cancer progression and immunosuppression." (PMID 34956861, 2021). "Finally, the combined blockage of both CD24 and CD47 confers an additive phagocytosis‐mediated cancer‐killing effect." (PMID 34363319, 2021). "Cancer cells with the CD44+/CD24−/ALDH1+ phenotype in breast cancer can therefore be distinguished from other cancer cells by their stem-like features, ability to maintain survival and the role in cancer invasion and metastasis, particularly in TNBC." (PMID 34944829, 2021). "CD24, which was originally identified as a B cell differentiation marker, has been indicated as a CSC marker in several tumors, such as ovarian, colorectal, bladder and urothelial cancers." (PMID 33889547, 2021). "Notably, the mRNA level of SLC27A6 was positively correlated with cancer stem cell (CSC) markers, CD24 and CD44." (PMID 35047398, 2021).
cancer (continued). "To quantify differences in frequency of putative cancer stem cell populations in both cell lines, we used flow cytometry to assess the enzymatic activity of aldehyde dehydrogenases (ALDH) and the expression level of the cell surface markers CD44 and CD24." (PMID 34367990, 2021). "The cancer stem cell marker CD44 scored positive in a small number (n = 8) of (CD24-negative) objects." (PMID 33801459, 2021). "The excessive LDs could upregulate CD24, CD44 expression and promote maintaining NPC CSC stemness, which could be a possible mechanism explaining why SLC27A6 overexpression promoted cancer metastasis." (PMID 35047398, 2021). "HOXB9 and CSC markers were simultaneously overexpressed in human refractory PCa tissues, compared with low-grade PCa, para-carcinoma, and initial PCa tissues implying the involvement of HOXB9 signalling’s involvement in ALDH+CD44+CXCR4+CD24+-PCa cell-rendered castration resistance." (PMID 34247196, 2021). "PDAC cells enriched with CD44, and/or CD24 and/or CD133 are highly tumorigenic-resistant to conventional anti-cancer therapy, and have been used as cancer stemness markers." (PMID 32457900, 2020). "This study demonstrated that CD24–Siglec-10 interaction apparently does not require sialic acids, while the removal of sialic acids from cancer cells also enhances phagocytosis by macrophages independent of CD24." (PMID 31900164, 2020). "Meanwhile, it was found that the markers of cancer stem cells (CSC) CD24 was significantly increased and no MET and HER amplications were detected in PC-9-Br compared to PC-9 parental." (PMID 32264860, 2020). "Importantly, higher expression of stemness genes including interleukin (IL)-6, EpCAM and CD24 was observed in HCC with lnc-DILC downregulation, indicating a positive correlation between lnc-DILC downregulation and increased cancer stemness properties." (PMID 32231294, 2020). "In addition, according to the results of Western blot experiments, MCF-7/SC were found to possess higher levels of cancer stem cell markers such as CD44, MRP1, and MDR1 and lower levels of CD24 compared with MCF-7 cells." (PMID 32503225, 2020). "Meanwhile, the potential toxicity of targeted CD24 to cancer patients cannot be ruled out at this stage." (PMID 32765491, 2020). "Siglec-10 binds to CD24, a ligand that, like CD47, is overexpressed in multiple human cancers." (PMID 31801627, 2019). "Although it is overexpressed in nearly 70% of human cancers, copy number variation of the CD24 locus has not been reported for any cancer." (PMID 31244889, 2019). "Despite functional role for CD24 in aspects of cancer development, there is no clinical evidence that CD24 expression is significant enough for cancer." (PMID 31244889, 2019). "Due to the high killing efficiency of CD24-specific NK cells against SKOV3 and OVCAR3 cells, we performed the following experiments to show the specificity of the killing effect of CD24-CAR-NK-92 cells in cancer cells." (PMID 30717444, 2019). "In the analysis of cancer stem cells marker, we found that the combination GSK461364 plus docetaxel decreased the number of CD44+/CD24-/dim in SUM149 (from 26% in DMSO to 18% after treatment) and SUM159 (from 89% in DMSO to 77% after treatment) compared to control (DMSO)." (PMID 31751384, 2019). "Obviously, while gene amplification provides a genetic fix that facilitates CD24 overexpression in the cancer cell, this is not the only mechanism by which CD24 is induced at high levels among cancer." (PMID 31244889, 2019). "While uncertainty exists about true nature of CSCs and their role cancer proliferation, in PDA, CSCs have been identified as being CD44+CD24+ESA+, CD133+/CXCR4+, or ALDHhighCD44+CD24− cells, where these cells are highly tumorigenic, promote metastatic spread, and are associated with poor survival." (PMID 29891787, 2018).
cancer (continued). "Compared to HER2 amplification in HER2-positive cancer cells, the increased levels of HER2 in the CD44+/CD24–/low BCSCs were relatively low because these changes may be associated with altered epigenetic regulation." (PMID 29464036, 2018). "Furthermore, during ethanol‐induced cellular transformation, cells gained the phenotypes of cancer stem cells (CSCs) by expressing pluripotency maintaining factors (Oct4, Sox2, cMyc and KLF4) and stem cell markers (CD24, CD44 and CD133)." (PMID 29761897, 2018). "In summary, we demonstrated that CD24 drives cancer stem-like traits and serves as a promising non-invasive urinary biomarker for UCB detection." (PMID 30327565, 2018). "To conclude, we analyzed the influence of CPEB1 on cancer stemness in HCC cells by analyzing self-renewal ability, chemoresistance, metastasis and expression of the stem cell-related genes OCT4, NANOG, SOX2, LIN28, CD24, EpCAM and CD133." (PMID 30237545, 2018). "Accordingly, we demonstrate that senescent HCT116 cells possess several properties of cancer stem cells, namely: elevated NANOG expression, increased Hoechst 33342 exclusion, increased CD24 expression, an ability to divide asymmetrically, clonogenic and spheroid-forming potential." (PMID 28030837, 2017). "We found that high CD44/CD24 ratio and ALDH1+ were related to cancer malignancy." (PMID 29062075, 2017). "Furthermore, we detected enhanced levels of at least one cancer stem cell (CSC) marker among CD133, CD24, and CD44 in 59% of the samples analyzed (n = 14)." (PMID 28700115, 2017). "In addition, the expression of CD24 and CD44 was higher in malignant tumors compared to that in an inflamed pancreatic tissue." (PMID 28659655, 2017). "This subpopulation of cancer cells can be isolated based on their Aldehyde Dehydrogenase (ALDH) enzymatic activity and the expression of different cell-surface markers, such as human Lin−CD44+CD24− and murine Lin−CD29HiCD24+." (PMID 28938607, 2017). "Moreover, treatment with siRNA-SMAD5 induced a luminal CD44-/CD24+ phenotype in MDA-MB 231 cells, indicating that SMAD5 expression is required to maintain a CD44+/CD24- cancer stem cell-like phenotype." (PMID 29207686, 2017). "Interestingly, several previously identified EOC cancer stem cell (CSC) markers, including CD44, CD24, CD117 (Kit), and EpCAM, were up-regulated in ID8-P1 vs. ID8-P0 cells." (PMID 29163813, 2017). "CD44+/CD24-/low stem cell/progenitor cells were isolated from normal and immortalised mammary cells (HMEC and MCF10A, respectively), LUM (MCF-7, HCC1428), HER2-E (MDA-MB-468, HCC1954) and TN (BT549, Hs578T and MDA-MB-231) cancer cells." (PMID 28202042, 2017). "It was observed that the CD24- CD44+ CSCs were also positive for expression of CD133 and TF, whereas non-CSC CD24- cancer cells were negative for express of CD133 (not shown)." (PMID 27903969, 2017). "Furthermore, while one would expect OCSC to represent a minor subpopulation of cancer cells, the prevalence of cells expressing putative CSC markers, such as CD44 and CD24, is often high in OC specimens." (PMID 28320418, 2017). "It has been widely reported that CD24-/CD44+ are the two cell surface markers used for isolating tumorigenic CSC from non-tumorigenic cancer cells." (PMID 27842518, 2016). "Moreover, we demonstrate here that the IGF1R is essential for the maintenance of stem/progenitor-like cancer cells and we further demonstrate that IGF1R-KD induces in vivo differentiation of the CD24+ cells toward the CD24- phenotype." (PMID 27179633, 2016). "The role of plasma membrane-bound CD24 in PDAC development remains unclear, yet is of particular interest, since surface CD24 expression serves as a cancer stem cell marker." (PMID 27203385, 2016). "Importantly, in our study the CD24+CD90+ TICs implanted into mammary glands were able to form macrometastases in lungs, therefore supporting the concept of EMT-generated metastatic cancer stem cells / TICs." (PMID 27542270, 2016).
cancer (continued). "Apparently the CD24+CD90+ cells are not expanding with the same speed as the other cell populations in the cancer." (PMID 27542270, 2016). "In fact, CD24 may affect the function of receptors such as CXCR4 and HER2, which are normally overexpressed in cancer cells." (PMID 26830684, 2016). "On the other hand, the negative selection of CD24 also has resulted in the selection of cancer stem cells in some other cancers such as breast and prostate." (PMID 27276062, 2016). "CD24 overexpression in HIF-1α-knockdown cancer cells rescued this decrease while HIF-1α overexpression in CD24-knockdown cells did not." (PMID 27706047, 2016). "We also detected the expression patterns of another cancer stem cell marker, CD24, in primary NPC and inflammatory tissues (data not shown)." (PMID 27647953, 2016). "More recently, MMTV-PyMT derived CD24+CD90+ cells have been instrumental to demonstrate the metastasis-supporting function of neutrophil granulocytes and for the elucidation of interaction of stroma and cancer cells during metastatic colonization." (PMID 27542270, 2016). "In PDAC, cells expressing surface CD24, CD44 and ESA were identified as putative cancer stem cells." (PMID 27203385, 2016). "Whereas CD24 can serve in certain cases as a marker for stemness, the IGF1R was found to play a crucial role in maintaining pluripotent properties of human embryonic stem cells; the self-renewal property of cancer stem cells." (PMID 27179633, 2016). "In addition, we further investigated the colocalization between ALDH1A1 and several cancer stem/progenitor markers (EpCAM, BMI1, CD13, CD24, CD90 and CD133) which have discovered recently to evaluate “stemness” in ALDH1A1-overexpressing cells in this report." (PMID 26160842, 2015). "Interestingly, it has been reported that Akt is activated in a specific subset of cancer stem cells that express CD133, CD44 and CD24." (PMID 26485768, 2015). "In our study we found only six familial BCs with CD44 positive/CD24 negative phenotype that defines cancer stem cells in BC." (PMID 26312763, 2015). "Others have demonstrated that this CD24 phenotype is not universal for all cancer models but it is more diverse and is affected by the driver mutation." (PMID 26040280, 2015). "In contrast, there are no spheres formed in non-cancer stem-like CD44-/CD24- cells after X-ray or carbon ion beam, either alone or in combination with CDDP." (PMID 26338199, 2015). "Interestingly, ALDH1A1 was not co-expressed with EpCAM, BMI1, CD13, CD24, CD90 and CD133 which have been reported to be cancer stem cell markers in HCC." (PMID 26160842, 2015). "Chemotherapy induces cancer cell apoptosis; our previous research indicated that chemotherapy-induced apoptosis may activate cancer stem-like cells (CD44+/CD24−) in MCF-7 and that upregulation of MUC1 occurred." (PMID 26016502, 2015). "Pancreatic CSCs identified with the marker profile ESA+/CD44+/CD24+ have the ability to form spheres in nonadherent conditions which distinguishes them from non-cancer stem cells which lack this ability." (PMID 24647545, 2014). "In the present study, we have isolated the CD24+/CD44+ population from HNSCC cell lines and determined whether this cell population has cancer stem cell properties by a variety of different approaches." (PMID 24612587, 2014). "While the EMT/MET genetic program has yet to be fully understood in cancer, recent studies showed that upregulation of two novel EMT key markers, CD44 and CD24, are necessary for entry into a mesenchymal-like state in highly drug resistant breast HER2 positive carcinoma." (PMID 24504051, 2014). "Breast CICs often express high levels of CD44 and lower levels of CD24 (CD44↑CD24↓) than the non-CIC population which is referred frequently to as the bulk cancer." (PMID 25051360, 2014).
cancer (continued). "On the other hand, cancer stem cells (CSCs) are characterized as a special group of cancer cells with enhanced tumorigenicity, partial stemness as in self-renewal and differentiation, and CD44+/CD24−/low on cell surface." (PMID 24805308, 2014). "The expressions of EpCAM, CD24, CD44, CD133, and CXCR4 antigens were membranous in carcinoma cells." (PMID 25240521, 2014). "CD24 has been investigated in combination with CD44 and other markers in various cancers." (PMID 22693526, 2012). "All markers identifying cancer stem cells are surface markers such as epithelial cell adhesion molecule (EpCAM), CD44, CD24, CD133 and C-X-C chemokine receptor type 4 (CXCR4) definitely expressed on the normal stem cells at the same time and apparently changing during cancer stem cell development." (PMID 22452810, 2012). "CD44, CD24, ESA, CD133, CXCR4 are the cancer stem cell marker for pancreatic cancer." (PMID 22082307, 2011). "CD44/CD24, CD29, CD133, CD200 are the cancer stem cell marker for breast cancer." (PMID 22082307, 2011). "These tumorigenic cells have been serially generated in new tumors containing additional CD44+ CD24-/low lineage tumorigenic cells as well as the phenotypically mixed population of non-tumorigenic cancer cells." (PMID 19014671, 2008). "We found that CD44+/CD24-/ESA+ cells exhibit properties of self-renewal in vitro, form tumors from very few cells, divide slowly, and are selectively resistant to chemotherapy, all of which are hallmarks of cancer stem cells." (PMID 18366788, 2008). "Furthermore, targeting of "do-not-eat-me" signals with anti-CD47 and anti-CD24 monoclonal antibodies demonstrate differential effects on macrophage activity and cancer cell viability, again depending on the individual malignant cell line." (PMID 41881987, 2026). "This review provides a comprehensive overview of the regulation and therapeutic targeting of immune checkpoint proteins in cancer, covering both classical checkpoints, including PD-1, PD-L1, and CTLA-4, and emerging targets such as LAG-3, TIM-3, TIGIT, BTLA, SIRP-α, CD200, ILT4, and CD24." (PMID 42279386, 2026). "RT-PCR results showed that the expression levels of CCL19, CD24, and ZIC2 were significantly higher in the MCF-7, ZR-75-1, and SK-BR-3 cell lines compared to the reference MCF-10A group, whereas the transcription level of CEBPD was significantly lower in the cancer cell lines (p < 0.05)." (PMID 40895068, 2025). "Specifically, from a prospective cohort of women with BI-RADS 4 breast lesions, we used TENPO to isolate both HER2+ EVs and CD24+ EVs and then performed next generation miRNA sequencing on each isolate to identify EV miRNA biomarkers that distinguish cancer versus noncancer patient samples." (PMID 40405296, 2025). "Finally, combining 015s with the CD24-targeted ADC cG7-MMAE yielded superior antitumour efficacy in the MC38-hCD24 colorectal model, providing initial proof that dual PD-1/TGF-β blockade can cooperate with ADC therapy in cancer treatment." (PMID 40806691, 2025). "Bispecific T-cell engagers (BiTEs) that target CD24/Siglec-10 and additional antigens like CD3 may also be a promising immunotherapeutic approach to pursue, since these molecules can also activate CD24-directed T cells to kill cancer cells." (PMID 38279998, 2024). "Moreover, the high content of CD44 and lack of CD24 were confirmed, which is related to cancer-like stem cell (CSC) features." (PMID 39408826, 2024). "Consistent with this notion, we found that the CD24 and CD49f surface markers, traditionally used to separate basal cells from luminal cells, could not effectively do so for the PyMT cancer cells." (PMID 38708713, 2024). "Moreover, cells were stained with CD24 and CD44 to assess the cancer stem-like phenotype." (PMID 38212739, 2024). "The authors concluded that CD24 and CD44 could not be used as specific cancer stem cell markers for prognostic or diagnostic purposes." (PMID 39684268, 2024).